EWSR1 (EWS RNA binding protein 1)
Diseases named in the same sentence as EWSR1 in open-access papers (continued):
Sharing a sentence is not in itself a finding about the gene and the disease.
Ewing sarcoma (continued). "The diagnostic hallmark for Ewing sarcoma is a rearrangement involving the EWSR1 gene, most commonly EWSR1-FLI1 and EWSR1-ERG rearrangements, while other rare translocation partners have been reported." (PMID 31897843, 2020). "In patients with localized or metastatic Ewing sarcoma (EWS), copy numbers of the EWSR1 fusion sequence in plasma were associated with tumor volume." (PMID 32010431, 2020). "For example, chromosomal translocation in the NFAT1 gene takes place in Ewing sarcoma, where there is formation of an amplified chimeric gene by frame-fusion with the Ewing sarcoma breakpoint region 1 (EWSR1) gene." (PMID 32397368, 2020). "Novel molecular alterations in patients presenting with tumours that histologically represent Ewing sarcoma, but lack the canonical EWSR1-ETS gene family translocation, have challenged how we approach diagnosis and classification of these tumours." (PMID 33488267, 2020). "The majority of respondents considered EWSR1-ETS gene family translocations (range 61–96%) to be Ewing sarcoma and would include them on the primary arm of a Ewing sarcoma clinical trial." (PMID 33488267, 2020). "Oncogenesis of Ewing sarcoma (EwS), the second most common malignant bone tumor of childhood and adolescence, is dependent on the expression of chimeric EWSR1‐ETS fusion oncogenes, most often EWSR1‐FLI1 (E/F)." (PMID 31811703, 2020). "Ewing sarcoma (ES) is a small round cell sarcoma showing gene fusions involving female expressed transcript (FET) family genes (usually EWSR1) and the erythroblast transformation-specific (ETS) family of transcription factors." (PMID 32867125, 2020). "Chromosomal translocations between the EWSR1 gene and genes encoding ETS transcription factors can cause aggressive pediatric tumors designated as Ewing sarcomas." (PMID 30967892, 2019). "Ewing sarcoma (EwS) is an aggressive cancer characterized by chromosomal translocations generating fusions of the EWSR1 gene with ETS transcription factors (in 85% FLI1)." (PMID 30741933, 2019). "Next, the Ewing sarcoma tumour is found to have EWSR1 (exon 10)-FLI1 (exon 8) translocation based on NGS." (PMID 30819134, 2019). "One case is particularly notable because the diagnosis of atypical Ewing sarcoma was made prior to the implementation of the comprehensive solid tumor panel and was supported by EWSR1 rearrangement by break apart FISH." (PMID 31133068, 2019). "Originally identified as the gene involved in the pathogenesis of Ewing sarcoma, the EWSR1 gene is now known to be rearranged in diverse clinical and histopathological entities." (PMID 31049020, 2019). "Here, we identified a murine gammaherpesvirus miRNA as critical for in vivo infection and validated the host mRNA EWSR1 (Ewing sarcoma breakpoint region 1) as the predominant target for this miRNA." (PMID 31363027, 2019). "These include CHEK2 mutations in breast cancers and also in a variety of other cancers including thyroid cancer, EWSR1 in Ewing sarcoma, RET in hereditary medullary thyroid carcinoma, NRP1 in breast cancer and germline POT1 variants in malignant melanoma." (PMID 31614935, 2019). "EWSR1/EWS is a multifunctional protein that is mostly known for its central role as a fusion protein in the genesis of Ewing’s sarcoma." (PMID 31363027, 2019). "Other subtypes of Ewing family sarcomas usually have fusion proteins derived from the translocations of EWSR1 (Ewing sarcoma breakpoint region 1, also known as EWS)." (PMID 30487384, 2018). "There are small blue round cell sarcomas in the Ewing sarcoma family in which EWSR1- or other known gene fusions have been observed." (PMID 30487384, 2018). "Among patients with newly diagnosed Ewing sarcoma withdetectable ctDNA, the median percent of total cell-free DNA that was ctDNAcontaining an EWSR1 translocation was 13.8%(range 1.4–43.2%)." (PMID 30131550, 2018).
Ewing sarcoma (continued). "Although CIC-DUX4- and BCOR-CCNB3-translocated sarcomas were shown previously to be distinct from EWSR1-ETS-translocated Ewing sarcomas, the situation was less clear for EWSR1-NFATc2-translocated sarcomas." (PMID 29416716, 2018). "Collectively, our data provide evidence that fast and robust diagnosis of Ewing sarcoma is enabled by immunohistochemical detection of the super-enhancer-driven EWSR1-ETS targets BCL11B and GLG1." (PMID 29416716, 2018). "Ewing’s sarcoma is genetically characterized by chromosomal translocation involving the Ewing’s sarcoma breakpoint region 1 (EWSR1) gene.." (PMID 29625604, 2018). "GLI1 is a direct transcriptional target of EWSR1-FLI1 oncoprotein which is a fusion transcript found in Ewing sarcoma family of tumors and consists of EWSR1 (RNA binding protein 1) and FLI1 (Fli-1 proto-oncogene, ETS transcription factor) genes." (PMID 30158435, 2018). "In particular, the high expression of the chosen markers was highly effective in discriminating Ewing sarcoma from EWSR1-ETS-negative Ewing-like sarcomas, which expressed CD99 at high levels in 88% of our cases." (PMID 29416716, 2018). "FLI1, the most common translocation partner of EWSR1 in the oncogenic fusion protein driving Ewing sarcoma, requires binding to transcriptional cofactor RNA Helicase A for full activity." (PMID 27732970, 2017). "Similar to Ewing sarcoma, DSRCTs present with an EWSR1 translocation that in DSRCTs fuses with the WT1 gene." (PMID 29050367, 2017). "For example, Ewing sarcomas with EWSR1-ERG fusions can be detected with the ERG antibody, although this is not specific, as other neoplasms (including vascular tumours, ERG-related myeloproliferative disorders and prostatic adenocarcinomas) express ERG." (PMID 28141799, 2017). "In 51/64 patients (79.7%), the conventional pathological diagnosis was complemented by cytogenetic analysis looking for Ewing sarcoma (EWSR1) gene rearrangement by fluorescent in situ hybridization (FISH)." (PMID 29527121, 2017). "Ewing’s sarcoma (ES) is a highly aggressive and metastatic tumor in children and young adults caused by a chromosomal fusion between the Ewing sarcoma breakpoint region 1 (EWSR1) gene and the transcription factor FLI1 gene." (PMID 27740934, 2017). "Ewing sarcoma is an aggressive bone and soft-tissue sarcoma that is defined by a recurrent chromosomal translocation between the EWSR1 and FLI1 genes." (PMID 29152060, 2017). "We have observed in OSA3 line not only a strong expression of the marker gene for the osteoblast differentiation, SATB2, but also a minimal expression of the EWSR1 gene, which is the principle marker gene for the Ewing Sarcoma." (PMID 27651797, 2016). "This translocation leads to the gene fusion between the 5′ segment of the EWSR1 gene (Ewing sarcoma breakpoint region 1) on the chromosome 22 and the 3′ portion of Fli1 (Friend leukemia virus integration site 1), located on the chromosome 11." (PMID 27006472, 2016). "Translocation of EWSR1 (Ewing sarcoma breakpoint region 1) with an ETS (E26 transformation-specific) transcription factor gene occurs in more than 95% of Ewing sarcomas." (PMID 27453756, 2016). "The Ewing sarcoma family of tumors expresses aberrant EWSR1- (EWS) fusion genes that are derived from chromosomal translocation." (PMID 27557633, 2016). "Ewing sarcoma is characterized by a quiet genome with presence of an EWSR1-ETS gene rearrangement as the only and defining genetic aberration." (PMID 26802024, 2016). "Despite this histogenetic uncertainty, Ewing sarcoma is genetically well characterized by the presence of pathognomonic EWSR1-ETS gene fusions (usually EWSR1-FLI1), which drive this disease by acting as oncogenic transcription factors." (PMID 26925391, 2016). "Biologically, Ewing sarcoma is characterized by recurrent balanced translocations involving the EWSR1 gene and a member of the ETS family of transcription factors, most commonly FLI-1." (PMID 28115942, 2016).
Ewing sarcoma (continued). "Much of the difficulty in identifying the tissue of origin for Ewing sarcoma arises from the toxicity of EWSR1-ETS fusion genes to most cell types." (PMID 26802024, 2016). "Ewing sarcoma tumors are defined by a recurrent chromosomal translocation between the EWSR1 gene and various ETS genes; the most common fusion, EWS-FLI1, is present in 85% of cases." (PMID 27557498, 2016). "KDM3A is up-regulated in Ewing sarcoma and this is at least in part as a result of EWSR1-Fli1 expression, which appears to act by repressing miR-22 and in turn de-repressing KDM3A." (PMID 26204834, 2015). "Almost all tumors of the Ewing sarcoma/PNET group have some form of EWSR1 (Ewing sarcoma breakpoint region 1) gene rearrangement, which is specific for this group of tumors." (PMID 25960901, 2015). "In this setting, demonstration of rearrangement of SSX18 or EWSR1 is crucial for differentiating respectively PDSS from Ewing Sarcoma/PNET." (PMID 25699170, 2015). "The identified key pathways in Ewing sarcoma and the EWSR1-ETS chromatin remodeling binding partners include promising candidate targets." (PMID 26193259, 2015). "The repression of IGF1R and mTOR by miR-100 and of IGF1a by miR-27a suggest post-transcriptional de-repression of the IGF pathway as an oncogenic mechanism in Ewing sarcoma, mediated by EWSR1-Fli1." (PMID 26204834, 2015). "Such an event would be analogous to the formation of EWSR1-DDIT3 in myxoid liposarcoma, EWSR1-ERG in Ewing sarcoma, and the EPC-PHF1, JAZF1-PHF1, and MEAF6-PHF1 fusions in endometrial stromal sarcoma." (PMID 25621995, 2015). "Using material from cohorts of genetically diagnosed Ewing sarcoma with EWSR1 chromosomal translocations, confocal images of tissue microarrays were segmented with level sets and watershed algorithms." (PMID 25243408, 2014). "Following total tumor resection, histological and molecular examination revealed Ewing sarcoma with rearranged EWSR-1 gene." (PMID 25614743, 2014). "PNETs belong to the Ewing’s sarcoma family of tumors, based on shared chromosomal translocation at EWSR1 (Ewing sarcoma breakpoint region 1)." (PMID 25475214, 2014). "EWSR1 rearrangements in Ewing's sarcoma have recently been shown to confer sensitivity to PARP-1 inhibition." (PMID 23637631, 2013). "By DBA, we identified intragenic breakpoints disrupting EWSR1 in Ewing sarcoma (ES6, EW12, EW22), neuroblastoma (GOTO, NBsusSR), and melanoma (CHL-1, SH4)." (PMID 23637631, 2013). "The fusion transcript EWSR1/FLI1 is present in more than 90 % of the Ewing sarcomas, and in the related group of peripheral primitive neuroectodermal tumor (pPNET), in rhabdomyosarcoma, in neuroblastoma and in giant cell tumor of bone." (PMID 23329308, 2013). "Rearrangements of the RNA binding protein, EWSR1, characterize various malignancies including Ewing sarcoma (EWSR1/ETS), desmoplastic small round cell tumor (EWSR1/WT1), and some acute lymphoblastic leukemias (EWSR1/ZNF384)." (PMID 23637631, 2013). "Many of these candidates also corresponded to known gene fusions, including EWSR1/FLI1 in Ewing sarcoma and ABL1 rearrangements in several leukemia samples." (PMID 23637631, 2013). "As in Ewing sarcoma, the chimerical protein included the EWSR1 N-terminal domain and the SP3 zinc finger DNA-binding domain but not the inhibitory domain of SP3-domain of WT1." (PMID 22587803, 2012). "Nearly every case of Ewing's sarcoma contains a translocation involving the EWSR1 gene on chromosome 22." (PMID 21437220, 2011). "However, in all four cases of Ewing sarcoma, the EWSR1/FLI1 fusion gene was detected either by RT-PCR or by NGS, leading to a revision of the initial diagnosis to positive." (PMID 40718211, 2025). "Indeed, in Ewing sarcoma cell lines and primary tumors, the vast majority of EWSR1::FLI1 binding sites are decorated by H3K27ac, a posttranslational histone modification associated with active enhancers." (PMID 41085408, 2025).
Ewing sarcoma (continued). "Ewing sarcoma is an undifferentiated small round cell sarcoma type having molecular markers as the translocation of a gene from the ETS family and EWSR1/FUS (a gene that encodes a protein that functions in gene expression, cell signaling, and RNA processing and transport) in some rare cases." (PMID 40932977, 2025). "Similarly, in a novel zebrafish model of Ewing sarcoma, targeted expression of EWSR1::FLI was uniquely tolerated in the neural crest and resulted in mesodermal reprogramming." (PMID 40983796, 2025). "Ewing sarcoma with EWSR1 gene rearrangement is presented as a prototypical example." (PMID 40666501, 2025). "The crucial role of EWSR1 in Ewing sarcoma has been extensively explored." (PMID 40510136, 2025). "FISH detected EWSR1 rearrangement, confirming Ewing’s sarcoma." (PMID 41250725, 2025). "In our series, we diagnosed a case of Ewing sarcoma confirmed by EWSR1 fusion by FISH." (PMID 39907157, 2025). "Despite international efforts over decades to develop a transgenic mouse model of Ewing sarcoma, attempts to induce the expression of EWSR1::FLI1 at the right level, in the right cell, and in the correct developmental state have proved very challenging and ultimately unsuccessful." (PMID 40858520, 2025). "Identifying an EWSR1/FUS::FLI1 gene fusion is pivotal in confirming Ewing’s sarcoma." (PMID 40860805, 2025). "However, CRISPR/Cas9-mediated gene editing can exhibit off-target effects, and thus, precise regulation of Cas9 expression in target cells is essential to develop gene-editing strategies to inactivate EWSR1 : : FLI1 in Ewing sarcoma cells." (PMID 40089636, 2025). "Interestingly, silencing EWSR1::ETS in seven Ewing sarcoma cell lines led to a reduction in the expression of nine of these 12 MTFs, suggesting their direct regulation by EWSR1::FLI1." (PMID 41444391, 2025). "Reference pathological analysis altered the diagnosis to Ewing sarcoma based on FISH analysis that revealed an EWSR1 translocation with an unknown partner." (PMID 40134582, 2025). "The most common fusion gene in Ewing sarcoma are EWSR1::FLI1 (85%) followed by EWSR1::ERG (10%)." (PMID 40666501, 2025). "The pathogenesis of renal Ewing sarcoma remains unclear, although some literature suggests it may be related to chromosomal translocation involving the EWSR1 gene." (PMID 40994948, 2025). "Recent studies of the TME of Ewing sarcoma, an aggressive fusion oncoprotein (EWSR1::FLI1)–driven primary bone tumor of adolescents and young adults, revealed the importance of extracellular matrix (ECM) remodeling and hypoxia in promoting Ewing sarcoma tumor cell survival and metastatic potential." (PMID 40858520, 2025). "CT-guided biopsy confirmed Ewing’s sarcoma with EWSR1 gene rearrangement." (PMID 41250725, 2025). "IHC expression of the protein most common fusion partner FLI1 may suggest the presence of a EWSR1-rearranged Ewing sarcoma of the kidney in about 60% of the cases, but is insufficient for diagnosis." (PMID 37999735, 2024). "The canonical genetic alteration among rare childhood tumors is the EWSR1 fusion in Ewing sarcoma." (PMID 38347552, 2024). "Notably, Ewing sarcoma cells tend to demonstrate heterogeneity between EWSR1/FLI1 high and EWSR1/FLI1 low states, and the latter cells have a stronger propensity to metastasize." (PMID 39594644, 2024). "Similar to EWSR1 in Ewing's sarcoma, FUS may be involved in chromosomal translocations, leading to the formation of fusion proteins." (PMID 39113127, 2024). "Additionally, copy number variations (CNVs) and fusion genes, such as the EWSR1/FLI1 fusion gene in Ewing sarcoma, play a crucial role in tumorigenesis." (PMID 39309469, 2024). "Overall, 100% of Ewing sarcoma patients have EWSR1 fusion proteins." (PMID 39090739, 2024). "Indeed, EWSR1 LCD has been shown to be required for transformation in Ewing sarcoma models, suggesting that the LCD-mediated self-association and phase separation is an important step in EWSR1-mediated oncogenesis." (PMID 39769457, 2024).
Ewing sarcoma (continued). "In Ewing sarcoma, EWSR1::FLI1 driven neogenes have been shown to be translated to neopeptides that are displayed on MHC and can be therapeutically targeted, increasing the probability that a similar therapeutic modality may be developed in DSRCT." (PMID 39139449, 2024). "In Ewing sarcoma cells, the fusion of EWS RNA binding protein 1 (EWSR1) and Friend leukemia integration 1 transcription factor (FLI1) EWS-FLI1 can increase transcription, replication stress and R-loop formation and lead to blocked BRCA1-mediated repair after DNA damage." (PMID 36750826, 2023). "Together, EWSR1::FLI1 utilizes at least three distinct mechanisms to promote Ewing sarcoma growth." (PMID 36672331, 2023). "To test this hypothesis, we used CRISPRi-mediated silencing of hnRNPH1 and EWSR1 in Ewing sarcoma cell lines." (PMID 36793594, 2023). "The main objective of this study was to identify genes that were downregulated by EWSR1::FLI1 in Ewing sarcoma that could be potentially relevant for the tumorigenesis process." (PMID 37511533, 2023). "The Ewing sarcoma breakpoint region one gene, also known as the Ewing sarcoma breakpoint region 1 (EWSR1) gene, is a member of the FET gene family (together with FUS/TLS and TAF15) and consists of a low-complexity PrLD and an SYGQ-rich N-terminal transactivation domain." (PMID 37426488, 2023). "CD44s is upregulated upon EWSR1::FLI1 knockdown in the A673 Ewing sarcoma cells." (PMID 37511533, 2023). "To evaluate this hypothesis, we engineered three Ewing sarcoma cell lines with a CD44s expression regulation system (that is, doxycycline-inducible), as it was the isoform preferentially overexpressed in the EWSR1::FLI1low phenotype." (PMID 37511533, 2023). "The chimeric EWSR1::FLI1 transcription factor is the main oncogenic event in Ewing sarcoma." (PMID 37511533, 2023). "By using the extensively studied A673/TR/shEF cell line, we showed that CD44 was dramatically upregulated upon EWSR1::FLI1 downregulation (that is, in the EWSR1::FLI1low phenotype), suggesting that CD44 is repressed by EWSR1::FLI1 in EWSR1::FLI1high Ewing sarcoma cells." (PMID 37511533, 2023). "The mechanism potentially involved in the negative regulation of CD44 expression in Ewing sarcoma under these conditions remains unknown, but it clearly correlates with the expression levels of EWSR1::FLI1 protein." (PMID 37511533, 2023). "While mesenchymal stem cells are a likely Ewing sarcoma cell of origin, the exact subset of these cells and their state when EWSR1/FLI1 forms is unknown." (PMID 34409300, 2021). "EWSR1 functions that are missing in Ewing sarcoma may offer an easier transition to growth and transcription regulation without this binding partner." (PMID 34035145, 2021). "Knowing the partner gene can be invaluable for the diagnostic dilemma such as seen with desmoplastic small round cell tumor (DSRCT) versus Ewing sarcoma since both might have fusions involving EWSR1 but with a different partner gene." (PMID 34514574, 2021). "Detection of the tumor-specific EWSR1/FUS-ETS fusion gene is essential to diagnose Ewing sarcoma." (PMID 34749732, 2021). "The EWSR1 gene is also commonly involved in oncogenic gene rearrangements in Ewing sarcoma." (PMID 34409300, 2021). "STAG2, a gene commonly altered in Ewing sarcoma and associated with a poor prognosis, was not altered in a single subject with EWSR1-NFATc2 positive sarcoma." (PMID 34021224, 2021). "The reported effects of EWSR1 fusion protein expression include: 1) altered epigenetic status due to aberrant recruitment of the chromatin remodeling complex, and 2) aberrant expression of target genes in Ewing sarcoma cells." (PMID 33293370, 2021). "Conventional Ewing sarcomas are characterized by the EWSR1-ETS translocation." (PMID 34441922, 2021).